MVP (major vault protein)
Diseases named in the same sentence as MVP in open-access papers (continued):
Sharing a sentence is not in itself a finding about the gene and the disease.
cancer (continued). "Major vault protein (MVP) interacts with miR-193a and promotes cancer development." (PMID 35563246, 2022). "Our previous study has found that YPFS could regulate p62/TRAF6 signaling, WT1/MVP axis and mTORC2/AKT signaling, which account the anti-MDR effects and anti-cancer effects both in vivo and in vitro models." (PMID 34135758, 2021). "Further comparative molecular analysis using the whole transcriptome microarrays for MVP-positive and MVP-negative cells showed that MVP is involved in regulating proliferation and migration of cancer cells." (PMID 34829999, 2021). "In cancer cells, RPN2 was described as being involved in the regulation of proliferation and migration, and in human airway smooth muscle cells, the protein MVP was found to be involved in growth/survival signaling pathways." (PMID 32283676, 2020). "Cancer cell lines originating from same organ often gathered in the same cluster, such as C2 [COAD/READ-STAD-PAAD], a group of digestive system cancers whose common features were the high expression of CNKSR1, FOLH1, ADGRG1, SMAD7, LRATD1 and MVP." (PMID 32874774, 2020). "Dozens of genes in cancer cell could contribute to intracellular distribution of DDP, e.g., multidrug resistant protein 1–3, breast cancer resistant protein, and MVP." (PMID 30131696, 2018). "It has been demonstrated that downregulation of P-gp and the major vault protein (MVP) could improve the cancer cells sensitivity to common chemotherapeutic agents and thereby reverse the drug resistance in some cancer cells." (PMID 29617302, 2018). "ARCaPM showed high levels of major vault protein (MVP or LRP) (P = 0.002, 1.41 log2 fold-change), a protein that is increased in advanced prostate cancer and expressed in drug resistant cell lines and various types of cancers." (PMID 28424404, 2017). "Similarly, MVP and genes encoding for Type I and Type II topoisomerases, such as TOP1, TOP2A, and TOP2B—known to contribute to cancer chemoresistance—showed the same negative association pattern." (PMID 40806276, 2025). "However, in our study, we found no specific correlation of MVP with cancer as it was found elevated also in infections and other types of inflammation." (PMID 39338437, 2024). "Contrary to the ample evidence for the role of MVP in multidrug resistance in cancer cells, some reports do not support this hypothesis." (PMID 27275002, 2016). "Moreover, MVP has been discovered on the surface of cancer cells, unlike in normal cells." (PMID 38651369, 2024). "Another recent paper reports on MVP being localized to the surface (referred to as csMVP) of various HCC cell lines and other cancer cells but not of normal hepatocytes." (PMID 33572350, 2021). "Unlike PARP4, MVP expression levels had no significant impact on overall patient survival, indicating a surprising and unanticipated vault-independent function of PARP4 in cancer." (PMID 39034402, 2024).
tumor (62 papers, 2002 to 2025). "The major vault protein significantly increased infiltration of M2-type tumor-associated macrophages in tumor tissues of HCC patients, promoting HCC proliferation, metastasis, and invasion through enhanced STAT6 activity." (PMID 41409600, 2025). "Elevated levels of circulating exosomal miR‐193a were thus associated with advanced disease, highlighting the role of MVP in selectively sorting miRNAs and promoting tumor progression." (PMID 40007074, 2025). "According to this model, in tumor cells, MVP associates with IRF2 and thereby promotes the secretion of pro-tumoral cytokines such as IL-4." (PMID 38264642, 2023). "We analyzed the relative expression of ABC-transporters’ genes ABCB1, ABCC1, and ABCG2, transcription factor YB-1 and MVP gene associated with the distribution of xenobiotics in cytoplasm, in 70 tumor samples." (PMID 35328603, 2022). "We have previously shown that high level of MVP associates with the tumor grade, while the level of the MVP transcript decreases." (PMID 34829999, 2021). "MVP is upregulated during malignant transformation and tumour progression and has been linked to chemoresistance." (PMID 27770278, 2017). "Analysis of miR-193a levels in tumours by qPCR indicated that MVP KO caused the accumulation of miR-193a in cells, with a concomitant decrease of miR-193a in the exosomes." (PMID 28211508, 2017). "MVP overexpression in most tumors is positively correlated with immune cell infiltration and a negative association with immunosuppressive cell infiltration, suggesting its significant role in enhancing tumor immune responsiveness." (PMID 40004027, 2025). "Moreover, we explored phosphorylation mutations of MVP in PAAD using the Clinical Proteomic Tumor Analysis Consortium (CPTAC) database." (PMID 39026679, 2024). "The researchers found that MVP promoted HCC proliferation and metastasis by regulating M2 polarization both in in vivo and in vitro, suggesting the potential involvement of MVP in modulating the tumor-associated macrophages (TAMs) within the tumor microenvironment (TME)." (PMID 39026679, 2024). "Accordingly, tumor-surrounding adipocytes are reported to induce multi-drug resistance through the upregulation of the expression of a transport-associated major vault protein (MVP) conferring a multi-drug resistance phenotype to BC cells." (PMID 31569710, 2019). "Research has found that major vault protein (MVP) regulates the transport of tumor suppressor miRNA, thereby promoting tumor migration." (PMID 40519928, 2025). "Reverse transcription quantitative polymerase chain reaction (RT-qPCR) analysis showed reduced MVP transcription in tumor samples compared to normal ones, whereas immunohistochemistry demonstrated elevated MVP levels, which correlated with higher tumor grades." (PMID 40004027, 2025). "Their findings revealed that the tumor suppressor miRNA miR‐193a, when prevented from entering exosomes due to the knockout of major vault protein (MVP), accumulated in donor cells and inhibited tumor progression." (PMID 40007074, 2025). "Consistently, in vivo experiments demonstrated that MVP knockdown inhibited tumor growth, as evidenced by reduced tumor volume, weight, and proliferation markers." (PMID 40586636, 2025). "Elevated MVP expression has been correlated with aggressive tumor phenotypes and poor outcome in many malignancies." (PMID 40004027, 2025). "While impaired DNA repair and disrupted apoptosis promote tumor progression and treatment resistance, MVP can co-regulate genomic stability, making it a potential target for radiotherapy resistance treatment." (PMID 40004027, 2025). "We first pointed out the abnormal upregulation of MVP in tumor tissues by immunohistochemistry, western blot, and reverse transcription‐quantitative polymerase chain reaction assays." (PMID 40586636, 2025). "Then we clarified the correlation between the expression of MVP and various kinds of tumor-infiltrating immune cells (TIICs) in PAAD." (PMID 39026679, 2024).
tumor (continued). "As we have known that immune regulation plays a key role in tumor initiation, growth, and treatment, herein, we carried out a multifaceted investigation to assess the relationship between MVP and immunity." (PMID 39026679, 2024). "Astrocytic-like CL4 and endothelial-like CL5 Mg-TAMs showed high signals in leading edge/infiltrating/cellular tumor and HyBV/MvP niches, respectively." (PMID 38566128, 2024). "This study systematically describes MVP as an immune-related biomarker with remarkable potential for predicting the prognosis, tumor progression and immunotherapeutic efficacy in PAAD." (PMID 39026679, 2024). "Immunofluorescence (IF) revealed that MVP expression was more significant in tumor tissues than ANT." (PMID 38264642, 2023). "The combined effect of elevated levels of MVP in HCC tumor and M2-like macrophages regulates HCC tumor microenvironment." (PMID 38264642, 2023). "Based on these results, we propose that MVP is a scaffold protein in tumor related signaling pathway." (PMID 38264642, 2023). "Among the three protein components of the vault complex, MVP is the most closely connected to tumor biology." (PMID 35681764, 2022). "In opposition to these observations, MVP was also reported to exert tumor suppressor properties in Lewis lung carcinoma cells." (PMID 35681764, 2022). "CAAs inducing the overexpression of MVP in tumor cells, increasing drug efflux and decreasing drug intracellular accumulation." (PMID 34095111, 2021). "Detection of immunohistochemical (IHC) reaction for MVP was demonstrated in all tissue types (control, tumor, metastasis)." (PMID 34829999, 2021). "The expression of the MVP in the control tissue and the primary tumor site shows a high degree of individual variation in relation to individual patients." (PMID 34829999, 2021). "For the TCGA-THCA cohort, the MVP mRNA expression in PTC was considerably correlated with tumor size (p = 0.00052), lymph node status (p = 2.2e-10), extrathyroidal invasion (p = 9.3e-09), and pathologic stages (p = 3.7e-07)." (PMID 35433709, 2021). "As to the cells’ mechanism of dispensing of this tumor-suppressive miR into exosomes, it was via the major vault protein (MVP), since the knockout of MVP resulted in the accumulation of the miR in the cells instead of the exosomes." (PMID 32092975, 2020). "High expression of MVP in these tumor cells is of particular interest since they are more likely to disseminate to give rise to chemoresistant metastases." (PMID 30654824, 2019). "We found that MVP was up-regulated significantly in tumor tissues compared with the matched tumor-adjacent normal tissues." (PMID 31092229, 2019). "A recent report has shown that major vault protein (MVP) regulated the sorting of tumor suppressive miRNA into EVs, which resulted in tumor progression." (PMID 30634952, 2019). "We observed a positive regulation of MVP expression at the tumor border, in regions that are in close contact with adipocytes, as compared with the tumor center." (PMID 30654824, 2019). "The up-regulation of MVP is likely triggered by the increased transcription activity in tumor cells." (PMID 31092229, 2019). "The requirement of MVP for the nuclear localization of tumor suppressor PTEN would lead to tumor cell cycle arrest." (PMID 31092229, 2019). "Expression of MVP in these tumor cells is particularly important because the cells present at the tumor border and within the stroma are more likely to disseminate to give rise to chemoresistant metastasis." (PMID 30654824, 2019). "MVP promotes IFNγ-mediated signalling, MAP kinase activity and neutrophil degranulation, while NGAL is a tumour-associated antigen involved in cell adhesion and innate immunity." (PMID 31366407, 2019). "Recently, scholars have innovatively proposed that major vault protein (MVP)-mediated tumor suppressor miRNAs can be selectively separated to the body to promote the development of the tumor process." (PMID 29552328, 2018).
tumor (continued). "For example, major vault protein (MVP) regulates sorting of tumor suppressive miR-193a into EVs, effectively removing it from cells and leading to more aggressive disease." (PMID 30071693, 2018). "The authors found that overexpression of MVP (major vault protein) transported miR-193a-3p from the tumor cells to exosomes." (PMID 29038785, 2017). "Knockout of MVP leads to miR-193a accumulation in the exosomal donor cells instead of exosomes, inhibiting tumour progression." (PMID 28211508, 2017). "MVP facilitates the nuclear tumour-suppressing function of PTEN in a Ca2+ dependent manner; nuclear PTEN is unable to inhibit PI3K signalling, leading to a more malignant phenotype." (PMID 27770278, 2017). "In summary, our data demonstrate that MVP-mediated selective sorting of tumour suppressor miRNA into exosomes promotes tumour progression." (PMID 28211508, 2017). "Collectively, these data suggest that MVP regulates miR-193a sorting into exosomes and that the accumulation of miR-193a in the exosomal donor cells as a result of KO MVP is detrimental to tumour cells." (PMID 28211508, 2017). "On the contrary, MVP knockout determined miR-193a-3p accumulation in tumor cells triggering the inhibition of cell proliferation and cell cycle G1 arrest due to miR-193a-3p binding to its target, caprin-1." (PMID 29038785, 2017). "We found that MVP expression is almost constitutively activated during malignant transformation in tumours of astrocytic origin and supports EGFR/PI3K signalling pathway activation leading to enhanced starvation resistance and migration/invasion potential." (PMID 24243798, 2013). "Strikingly, MVP-overexpression induced distinct tissue invasion into normal brain with fissured margins and multiple Ki-67-positive tumour islets invading the surrounding brain parenchyma." (PMID 24243798, 2013). "MVP overexpression (those tumours with moderate or strong expression of the protein) was related to insulin-like growth factor receptor-1 (IGF-1R) expression (P = 0.014)." (PMID 22931894, 2012). "The level of MVP expression predicts the clinical outcome after chemotherapy in different tumour types." (PMID 22040803, 2011). "The anti-major vault protein Fab was found suitable for immunohistochemical and Western blot analysis of tumour cell lines and human tissues." (PMID 11953829, 2002). "Only five resistance proteins (MDR1, TYMS, GSTP1, MGMT, MVP/LRP) were increased in comparison to sensitive tumours, while the other resistance factors revealed only marginal changes." (PMID 12177790, 2002). "Collectively, knockdown of MVP suppressed tumor growth of TSCC in vivo." (PMID 40586636, 2025). "KEGG analysis indicates that “pancreatic secretion”, “fat digestion and absorption”, and “glycosphingolipid biosynthesis” might be involved in the role of MVP in tumor pathogenesis of PAAD." (PMID 39026679, 2024). "Importantly, MVP expression demonstrated a close relationship with immune infiltration in the tumor microenvironment, showing that higher expression levels were associated with increased immune cell infiltration." (PMID 38713157, 2024). "Indeed, an independent study demonstrated that B7-H3 expression increased the number of BC stem cells through the major vault protein (MVP), thus promoting tumor development." (PMID 36901916, 2023). "The most intense immunoreactivity to MVP was in tissues with metastatic tumor cells." (PMID 34829999, 2021). "Moreover, MVP is involved in pathways related to tumor development and multi-drug resistance, such as PI3K/AKT, MAPK/ERK, and the Notch signaling pathways." (PMID 33637972, 2021). "MVP upregulation promotes oncogenesis and development of multiple tumor types." (PMID 35433709, 2021). "Therefore, increased expression of MVP in tumor cells induced by adipocytes increases drug efflux and decreases drug intracellular accumulation." (PMID 34095111, 2021).
tumor (continued). "There were no obvious changes in tumor-associated macrophages accumulation, polarization and neutrophils recruitment in MVP knockdown tumors." (PMID 31092229, 2019). "Finally, MVP expression was increased in tumor cells cocultivated with mammary adipocytes as compared with control cells and this effect was more pronounced in obese conditions." (PMID 30654824, 2019). "However, mice injected subcutaneously with MVP KO SW620 cells have a much slower tumour growth rate." (PMID 28211508, 2017). "The activity of cellular machinery for sorting tumour suppressor miRNA into exosomes may cross-talk/communicate with a family of oncogenic factors, such as MVP, which we identified in this study." (PMID 28211508, 2017). "MVP binds to tumour suppressor miR-193a, forming an MVP protein-miR-193a complex." (PMID 28211508, 2017). "We cannot exclude the possibility that MVP may target other miRNAs, in particular other tumour suppressor miRNAs, subsequently regulating sorting of these tumour suppressor miRNAs into exosomes." (PMID 28211508, 2017). "MVP expression was studied by immunohistochemistry in paraffin-embedded tumour tissue." (PMID 22931894, 2012). "Furthermore, several studies reported that the expression of MVP is a predictive marker in several tumour types for the response to chemotherapy." (PMID 22040803, 2011). "Concomitant operation of several drug resistance mechanisms may often be necessary to cause the phenotype of MDR, and co-expression of MVP and ABCC1 frequently occurs and associates with increased drug resistance levels in MDR-selected tumour cells." (PMID 22040803, 2011). "Transfection of this new construct into MVP-positive tumour cells then might lead to blockage of the MVP protein, e.g. due to binding of the Fab to the epitope during protein synthesis, and thus interfere with vault assembly and/or function." (PMID 11953829, 2002). "Thus, MVP is not only high expressed in tumor cells but also in M2-like macrophages." (PMID 38264642, 2023). "In addition, based on functional enrichment analysis, we carried out a series of cellular and molecular assays to explore the connection between MVP and tumor immune-related molecular characteristics and to demonstrate the effects of knockdown and over-expressed MVP on PTC cell lines." (PMID 35433709, 2021). "Analysis of the TCGA database revealed that the increased MVP expression was consistent with more malignant clinicopathological features, involving larger tumor, more extensive LNM, and higher tumor stage, and extrathyroidal invasion implied that MVP might be bound up with the progression of PTC." (PMID 35433709, 2021). "Therefore, it is speculated that accumulation of miR-193a in tumour cells by knockdown of MVP may prevent exosome release, thus contributing to inhibition of tumour progression as well." (PMID 28211508, 2017). "Among them, higher levels of major vault protein (MVP), disulfide-isomerase A6 (PDIA6), and hnRNP A1 were detected in GBM tumor tissues than in normal tissues (Gene Expression Profiling Interactive Analysis database)." (PMID 40340965, 2025). "Specifically, SIRT7 acts as a desuccinylase targeting MVP at K437, which in turn activates JAK2/STAT3 signaling to drive tumor cell proliferation, migration, and invasion." (PMID 40586636, 2025). "In summary, knockdown of MVP in PAAD cell lines impairs cell proliferation and migration abilities, accelerates cell apoptosis, and thereby inhibits the tumor progression, which strongly supports the results of our bioinformatics analyses." (PMID 39026679, 2024). "Our results indicated a notable increase in both protein abundance and protein phosphorylation of MVP gene at the s445 site in PAAD samples compared to normal tissues, suggesting its potential involvement in the malignant development of the tumor." (PMID 39026679, 2024).